CFTR (CF transmembrane conductance regulator)
Diseases named in the same sentence as CFTR in open-access papers (continued):
Sharing a sentence is not in itself a finding about the gene and the disease.
lung disease (continued). "In addition, the impact of highly effective CFTR modulator therapies on Aspergillus lung disease in CF is as yet unclear." (PMID 39330359, 2024). "Despite the clinical benefits of CFTR modulators, clonal lineages of P. aeruginosa persist that may prove just as difficult to manage in the future, especially in pwCF with advanced lung disease." (PMID 38442240, 2024). "Furthermore, a large repertoire of exploratory endpoints testing more sensitive lung function measurements should be included in clinical trials given the complex tasks of CFTR function and how they lead to lung function decline and lung disease." (PMID 39439894, 2024). "Deciphering the link between CFTR dysfunction and bacterial infection in CF airways may reveal the pathogenesis of CF lung disease and guide the development of new treatments." (PMID 38699141, 2024). "Similarly, a study found a non-linear, logarithmic relationship between CFTR activity (predicted by variant status) and lung function, suggesting that even small increases in functional CFTR would provide vast improvement in people with severe lung disease." (PMID 39439894, 2024). "In CF, also a genetic condition associated with lung disease and abnormal ciliary-mucus interactions, cellular stress due to the CFTR F508del variant (in the absence of infection) is proposed to contribute to lung disease progression." (PMID 39042459, 2024). "Burgel and collaborators used a French compassionate program to assess for 4–6 weeks the effectiveness of ETI therapy in 84 PwCF (16 children and 68 adults) with advanced lung disease and carrying no F508del-CFTR in their alleles." (PMID 36986509, 2023). "The introduction of the CFTR modulator therapy may not only explain the pleiotropic effects of these drugs but also elucidate the pathophysiology of lung disease in PWCF." (PMID 37895314, 2023). "Effects of CFTR modulator treatment on lung disease progression in paediatric subjects." (PMID 37113757, 2023). "Conversely, targeting secretory and basal cells could restore CFTR-mediated secretion of chloride and bicarbonate to prevent the typical clinical symptoms of CF lung disease." (PMID 37843282, 2023). "Thus, there exists ample evidence that ENaC/CFTR genotypes contribute to lung disease and specifically bronchiectasis, and that a CF-like syndrome can be associated with CFTR and ENaC mutations acting either in concert or individually." (PMID 37175488, 2023). "While several data have been endorsed as a useful endpoint in clinical trials of patients with early or mild CF lung disease and as the main outcome measure in clinical trials with CFTR modulators in children and adolescents with CF, few data are available in the context of non-CF bronchiectasis." (PMID 37238339, 2023). "Therefore, the aim of this real life study was to investigate the effects of CFTR modulator therapy on structural lung disease, using different CT analysis methods specific for CF lung disease." (PMID 37113757, 2023). "Effects of CFTR modulator treatment on lung disease progression across all subjects." (PMID 37113757, 2023). "Neither gender, prior CFTR modulator therapy, nor BMI or degree of lung disease severity at baseline was associated with ppFEV1 gains at 3 or 12 months." (PMID 37469865, 2023). "While effective at slowing the progression of lung disease, these therapeutic approaches failed to address the root cause of the disease, CFTR dysfunction." (PMID 36142171, 2022). "Further studies are needed to define whether the slowing down or reversion of severe pulmonary disease could be obtained in pwCF, and whether more people with severe CF will gain life-changing benefits from CFTR modulation." (PMID 35207295, 2022). "Effective gene therapies for CF lung disease have been pursued since the discovery of CFTR in 1989." (PMID 36304167, 2022).
lung disease (continued). "Besides a functional recovery of CFTR, also lung disease relevant parameters were normalized, such as airway mucus viscosity, mucociliary clearance and ASL height, the latter implying a restored hydration of the airways." (PMID 33986686, 2021). "In the early 1990s, there was evidence that, although the CFTR mutation class was a fairly good predictor of pancreatic disease associated with CF, this did not prove to be true for CF lung disease." (PMID 34945117, 2021). "Our findings suggest that the airway inflammation that characterizes CF lung disease plays a major role in the positive clinical responses to CFTR modulator therapy, and we propose a model with a direct relationship between airway inflammation and CFTR rescue." (PMID 33859562, 2021). "Of 114 CF twin and sibling pairs homozygous for Phe508del that were included in the European twin and sibling study, monozygous twins showed more concordance in lung function than dizygous twins, indicating that inherited factors modulate lung disease severity in addition to the CFTR genotype." (PMID 34070354, 2021). "Besides the possibility to correct molecular and functional end-points related to CFTR activity, these KO models and in particular those with a prominent lung phenotype, allow studying a possible improvement of human-relevant lung disease." (PMID 33986686, 2021). "In the early 1990s, there was evidence that, although the CFTR mutation class was a fairly good predictor of pancreatic disease associated with CF, this was not the case with CF lung disease." (PMID 34945117, 2021). "With the aim to develop Esc peptides or derivatives as novel multifunctional drug candidates for ideal treatment of CF pulmonary disease, here we investigated their ability to affect ion currents controlled by CFTR by combining different electrophysiological techniques and computational studies." (PMID 34971429, 2021). "Early CF lung disease is highly variable, even in children with the same CFTR genotype." (PMID 34070354, 2021). "Since mutations in SLC34A2 which reduce phosphate transport are linked to lung disease, we speculate that any SNPs which alter SLC34A2 activity might indirectly affect F508del-CFTR function and potentially impact the outcome of CFTR corrector therapies." (PMID 34020896, 2021). "In addition, the autophagic dysfunction-mediated cystic fibrosis transmembrane conductance regulator (CFTR) immune response impairment further exacerbates the lung disease." (PMID 32847034, 2020). "This has enabled many CF research groups to look to CF primary airway epithelial cell models in order to understand the cellular drivers of progressive lung disease, and more recently to evaluate the efficacy of CFTR modulators in restoring CFTR function in target cells." (PMID 32318073, 2020). "Thus, the most exciting aspect of CFTR modulator therapy is its potential for ameliorating lung disease as discussed in detail elsewhere." (PMID 32276344, 2020). "Thus, correcting the underlying proteostasis and autophagy defect in controlling CF pulmonary disease, primarily via correcting the protein processing defect of F508del-CFTR protein has emerged as a novel intervention strategy." (PMID 30774592, 2019). "Increased TGF-β1 signaling and acquired CFTR dysfunction are present in other lung diseases." (PMID 31590401, 2019). "Finally, identification of specific HDACs that control CFTR processing and lung disease, would lead to the development of selective HDAC-inhibitor drugs." (PMID 29301535, 2018). "Nevertheless, further screening and testing of novel compounds in a personalized setting may lead to improvement of CFTR function and reduction of lung disease in COPD patients." (PMID 29540993, 2018). "CFTR−/− rats recapitulate important features of lung disease that are observed in humans with CF." (PMID 29609604, 2018). "CFTR dysfunction and chronic airway inflammation drives the pathogenesis of CF-lung disease." (PMID 29301535, 2018).
lung disease (continued). "For example, even for a monogenetic disease such as CF, mouse models developed by knocking out the causative gene CFTR across a variety of genetic backgrounds failed to recapitulate spontaneous lung disease." (PMID 29077751, 2017). "In the CF genetic disease, the great majority of patients (80%) carries P. aeruginosa infection but the progression and severity of pulmonary disease is not strictly correlated with the CF transmembrane conductance regulator (CFTR) gene mutations." (PMID 27848994, 2016). "CFTR genotype alone may correlate poorly to lung disease and environmental factors and modifier genes may also be important for disease severity." (PMID 27280467, 2016). "Our results indicate that highly mucoid type 3 Sp causes more severe lung disease than non-mucoid Sp, and does so more readily in the lungs of CFTR–/– than WT-mice." (PMID 26469863, 2015). "CFTR expression was shown to be restricted to the intestines and CFTR-/-;TgFABP>pCFTR pigs were able to survive longer than 9 months developing spontaneous lung disease." (PMID 26600426, 2015). "A body of evidence suggests that even modest amounts of CFTR expression may suffice to improve lung disease." (PMID 25838137, 2015). "Our findings may also point to a new direction in elucidating the mechanisms of decreased CFTR function in lung diseases resulting from cigarette smoke inhalation." (PMID 24727471, 2014). "According to the current hypothesis in CF pathogenesis of the lung disease, we demonstrate that hAMSCs can increase the F508del CFTR-dependent chloride secretion and diminish the fluid hyper-absorption." (PMID 24894806, 2014). "CFTR potentiators such as ivacaftor represent an attractive therapeutic approach for individuals with smoking related lung disease and may be particularly well suited to individuals with chronic mucus hypersecretion." (PMID 22768130, 2012). "The rationale for developing gene therapy and small molecule drug corrector approaches to treat CF lung disease is the reported absence of CFTR from the apical membrane of airway epithelium in the commonest mutation, CFTR-delF508." (PMID 21826241, 2011). "Although the CFTR KO mouse utilized in this study does not develop spontaneous lung disease, it is an ideal model system to examine the effects of CFTR transport deficiency without the confounding effects of lung damage and excess inflammation." (PMID 20799947, 2010). "Although greater than 1000 mutations of the CF gene product, CFTR are known, none of these can be used to make predictions about the occurrence of common complications, the severity, or course of pulmonary disease." (PMID 15507145, 2004). "However, which defective CFTR function primarily leads to CF lung diseases remains in debate." (PMID 38699141, 2024). "CFTR is also expressed in immune cells, such as neutrophils, monocytes and macrophages, but it remains unclear whether CFTR dysfunction disrupts the immune response of these cells and whether this significantly contributes to the development of CF lung disease." (PMID 38699141, 2024). "We provide an overview on inflammatory/immunity gene variants that affect CFLD severity and an appraisal of the effects of CFTR modulator therapies on the inflammatory process in lung disease and how this knowledge may advance the optimization of the management of PWCF." (PMID 37895314, 2023). "Utilizing our co-culture system, mechanistic studies into the effects of CFTR modulators on bacterial survival due to changes in mucus characteristics can be investigated, and will provide important considerations for optimizing therapies for pwCF and other lung diseases." (PMID 37998353, 2023). "Highly-effective CFTR modulators such as Elexacaftor/Tezacaftor/Ivacaftor (Trikafta®) and Ivacaftor (Kalydeco®) are the most effective treatment options for eligible individuals with CF and they have the potential to prevent moderate-to-severe lung disease if initiated earlier in life." (PMID 37264136, 2023).
lung disease (continued). "With expanding use of highly effective CFTR modulatory therapy among younger patients with CF, including recent approval for elexacaftor/tezacaftor/ivacaftor for ages two and above, the natural history of the onset and progression of lung disease in young children is likely to change." (PMID 37809107, 2023). "However, CFTR modulator treatments are not curative and lung disease associated with continued cycles of infection and inflammation remains." (PMID 37137509, 2023). "Therefore, animal models further helped to recapitulate the complexity of CF disease and to study the molecular mechanisms of the changes and IgA-related immunity acquired in the airways of CF patients, but currently mouse models mostly fail to reproduce intrinsic, CFTR-related lung disease." (PMID 34944110, 2021). "Moreover, those CF patients with ‘mild’ mutations and residual CFTR function have less severe lung disease indicating that not all cells are required to be corrected." (PMID 34084147, 2021). "Thus, despite the dramatic impact that CFTR modulator therapy will likely have on the natural history of CF lung disease over the coming years, considering the central role of inflammation in lung damage, research focused on the control of the inflammatory process still remains a priority." (PMID 33669352, 2021). "In addition to CFTR modulators, progress has been made in developing cell-based and gene-based therapies for CF lung disease." (PMID 32153386, 2019). "However, expression of CFTR mRNA was similar at baseline in the three lung diseases and controls." (PMID 31590401, 2019). "Therefore, it is important to establish the mechanisms involved in CFTR-related inflammatory responses and whether alleviation of inflammatory responses is beneficial in the management of CF lung disease." (PMID 29540993, 2018). "Analysis of CFTR and 13 lung disease modifier genes shows DNA methylation changes of small magnitude: some of them are a consequence of the disease; other changes may result in small expression variations that collectively modulate the lung disease severity." (PMID 28289476, 2017). "On the contrary, the role of DGA in stabilizing the structure of Ace may be of therapeutic benefit in epithelia lacking normal CFTR function that cause lung disease like CF." (PMID 26540279, 2015). "Second, individuals with CF with certain “mild” mutations that retain as little as 10% of normal CFTR expression per cell generally do not suffer from lung disease, although other organs such as the vas deferens may be affected." (PMID 25838137, 2015). "This study demonstrates that the genetic background has a substantial influence on CFTR activity in murine airways, and that genetically determined differences in CFTR function have profound effects on the severity of dehydration-induced lung disease in βENaC-Tg mice." (PMID 22937152, 2012). "It is well-accepted that the diversity of lung disease among CF patients is not accounted for either by variation in CFTR mutations or by level of sweat chloride as there is considerable phenotypic heterogeneity even in patients with the same class of CFTR mutation." (PMID 20420703, 2010). "Recent improvement in survival is primarily due to the advances in therapeutics, that is, cystic fibrosis transmembrane conductance regulator (CFTR) modulators, or CFTR corrector and potentiator medications, which ameliorate pulmonary disease." (PMID 39832355, 2025). "We hypothesized that individuals with elevated sweat chlorides but without any pathogenic CFTR variants would manifest with less severe pulmonary disease and fewer extra-pulmonary manifestations, as CFTR dysfunction alone may not be responsible for their symptoms." (PMID 41318507, 2025).
lung disease (continued). "However, despite the clinical efficacy of current CFTR modulators in restoring the activity of defective CFTR, some patients cannot be treated or show persistent pulmonary infections (mainly due to P. aeruginosa) that remain a major challenge, mostly in advanced stages of lung disease." (PMID 40100363, 2025). "To evaluate the effectiveness of LUM/IVA therapy in preventing the development of lung disease, we assessed the bacterial flora in the bronchioalveolar lavage fluid (BALF) of CFTR-F508del ferrets." (PMID 38646935, 2024). "Recognizing that CF is more than just a lung disease and understanding that modulator therapies may influence the progression of pulmonary disease necessitates prospective clinical studies to examine the impact of novel CFTR modulators on various CF-related complications, including CFLD." (PMID 38473009, 2024). "Direct interactors with the CFTR protein, including SNAP23, KRT19, PPP2R1A, and PPP2R4 proteins, were also identified as lung disease modifiers in a longitudinal study." (PMID 40225935, 2024). "Percentage predicted FEV1 is the most commonly studied marker for progression of lung disease patients with CF, and the equivalent measure (FEV0.4) in CFTR-F508del ferrets was also significantly lower than WT controls." (PMID 38646935, 2024). "Among these models, the CFTRG551D/G551D ferret was the first to evaluate CFTR modulator therapy in utero and postnatally, demonstrating the safety and efficacy of IVA therapy to protect from MI, pancreatitis, and lung disease." (PMID 38646935, 2024). "In addition, people with mutations associated with as little as 10% residual CFTR function may have mild disease phenotypes, including little or no lung disease." (PMID 34520545, 2021). "Allelic variants of CFTR mutations do not explain the wide variation in the severity of lung disease; however, studies on twins and siblings show substantial heritability (h > 0.5), highlighting differences that may exist when performing lung function measurements in CF patients." (PMID 34945117, 2021). "Altogether, these data not only highlight the impact of SLC26A9 expression in lung disease and response to CFTR modulator drugs but also motivated our research on the interaction between SLC26A9 and CFTR." (PMID 34884866, 2021). "For example, non-CFTR modifier genes, including TGF-β1, affect the severity of the CF lung disease in F508del homozygous individuals." (PMID 31590401, 2019). "CFTR−/−, CFTRΔF508/ΔF508 and CFTR-/ΔF508 pig strains (hereafter collectively referred to as CF pigs) spontaneously develop key features of human CF lung disease within months of birth." (PMID 29609604, 2018). "Recapitulation of key CF airway features in the CFTR−/− rat model including reduced ASL and MCT will provide opportunities to further investigate the mechanisms involved in lung disease development." (PMID 29609604, 2018). "There remains a need for a simple, reliable bronchoscopy scoring tool to assess lung disease severity in children who are not eligible for CFTR modulator therapy, in order to support optimal clinical management." (PMID 41467470, 2026). "Initial research development and clinical trials of CFTR modulators did not include much representation from people with advanced lung disease or those who required transplantation." (PMID 40144821, 2025). "CFTR knockout mice do not develop the typical lung disease phenotype seen in humans with CF, which is probably at least partially attributable to up-regulation of the alternative chloride channels." (PMID 36304167, 2022). "The confirmation of the expression of CFTR in non-epithelial cells and the significance of inflammation in the progression of CF lung disease have raised interest in the role of immune cells in CF." (PMID 34943888, 2021).